FOXA1 (forkhead box A1)
Diseases named in the same sentence as FOXA1 in open-access papers (continued):
Sharing a sentence is not in itself a finding about the gene and the disease.
liver cancer (37 papers, 2012 to 2026). An epithelial or non-epithelial malignant neoplasm that arises from the liver. "Foxa gene family members are contributors to sex disparity in liver cancer and female Foxa1/2-deficient livers are prone to HCC as male livers." (PMID 40568073, 2025). "Studies have indicated that Foxa1/2 deficient female mice are more susceptible to DEN-induced liver cancer development because of the loss of the interaction between Foxa1/2 and ERα." (PMID 26701855, 2016). "A recent study showed that β-catenin can down-regulate ARG1 expression by suppressing liver-enriched transcription factors C/EBPA and FOXA1 in liver cancer cell lines." (PMID 41512056, 2026). "We emphasize the need to validate our findings in other liver cancer cell lines, especially HCC-specific cell lines to confirm the role of FOXA1 in the development of resistance in different types of liver cancer." (PMID 40216647, 2025). "Our results suggest a possible role of FOXA1 and miRNA-212-3p in the development of resistance to chemotherapeutic drugs in liver cancer and the possibility of their use as prognostic and/or therapeutic targets." (PMID 40216647, 2025). "Changes detected in the tested EMT genes point to progression toward more aggressive behavior in the doxorubicin-resistant liver cancer cell line that was reversed with inhibition of FOXA1." (PMID 40216647, 2025). "Loss of Foxa1 and Foxa2 expression in female liver affects ERα binding to its targeted genes and thus increases DEN-induced liver cancer in female mice." (PMID 40568073, 2025). "Our previous studies on doxorubicin-resistant liver cancer cell lines identified the Fork head box A1 (FOXA1) gene as a possible player in doxorubicin resistance." (PMID 40216647, 2025). "Upregulation of the Forkhead box A1 transcription regulator in our model of doxorubicin-resistant liver cancer cell line suggested a role in resistance." (PMID 40216647, 2025). "Our study aims to assess the impact of doxorubicin on the survival of liver cancer cell lines after knocking down FOXA1 using an siRNA silencer or increasing inhibitory miRNA-212-3p expression." (PMID 40216647, 2025). "Srsf3 KO in our study decreased the expression of ERα and Foxa1–3 and its downstream genes Lifr and Egfr but increased Myc expression both in female and male livers, thereby promoting liver cancer formation by disrupting sex disparity." (PMID 40568073, 2025). "In this study, we clarified that HAL was transcriptionally induced by CEBPA and FOXA1, and that their expression levels were down-regulated by the Wnt/β-catenin signaling in the liver cancer cells." (PMID 38684876, 2024). "In this study, we have shown that the promoter region of HAL was transcriptionally regulated by transcription factors CEBPA and FOXA1, and that the two were down-regulated by the Wnt signaling pathway in the liver cancer cells." (PMID 38684876, 2024). "FOXA1 is a transcription factor that affects cancer initiation and promotion in several cancers, such as breast, endometrium, prostate, lung, and liver cancers." (PMID 39000600, 2024). "The results from quantitative reverse transcription–PCR (RT–qPCR) and Western blot experiments showed that the expression of FOXA1 in liver cancer cell lines was higher than that in immortalized human liver cell lines." (PMID 35968505, 2022). "The GSEA results suggest that FOXA1 promotes the progression of liver cancer by promoting the proliferation and metastasis of HCC cells." (PMID 35968505, 2022). "Some studies have found that FOXA1 plays an important role in the occurrence and development of liver cancer, but few studies have recently focused on this topic." (PMID 35968505, 2022). "Proliferation, wound healing, and Transwell experiments showed that FOXA1 enhanced the proliferation and migration abilities of liver cancer and immortalized human cell lines." (PMID 35968505, 2022).
liver cancer (continued). "There are obvious gender differences in HCC mice induced by DEN, and the defects of Foxa1 and Foxa2 can reverse this gender difference relative to the incidence of liver cancer." (PMID 35096574, 2021). "For instance, MCM3AP-AS1 is up-regulated in liver cancer and can target miR-194-5p/FOXA1 axis to promote cancer growth." (PMID 31985002, 2020). "Focusing on the tumor suppressive roles, FoxA1 inhibited liver cancer cell invasion via up-regulation of microRNA-122 (miR-122)." (PMID 32151057, 2020). "For example, sexual dimorphism in liver cancer is determined by differential target activation depending on Foxa1/2 and AR or ERa interactions." (PMID 31350899, 2019). "Accordingly, FOXA1 expression is highest in normal liver and intestine epithelium as well as breast, prostate, gastrointestinal and liver cancer cell lines amongst a panel of 562 samples analyzed by the FANTOM5 consortium." (PMID 29669022, 2018). "Although the underlying mechanisms governing the FOXA1-AR correlation in tumor progression are not fully understood, a pathway analysis showed that 187 FOXA1/AR dual target genes were involved in the cellular growth/proliferation pathway in liver cancer." (PMID 24512546, 2014). "Pathway analysis in liver cancer shows that FOXA1/AR dual target genes are most involved in the cellular growth/proliferation pathway." (PMID 24512546, 2014). "The modulation of FOXA1 and its downstream effectors presents a promising strategy for enhancing the efficacy of current chemotherapy regimens and offers hope for better clinical management of liver cancer." (PMID 40216647, 2025). "Finally, combining FOXA1 silencing or miRNA-212-3p mimic with doxorubicin resulted in a fourfold increase in apoptosis induction in HepG2/Dox cells, suggesting that targeting FOXA1 can effectively restore drug sensitivity in resistant liver cancer cells." (PMID 40216647, 2025). "Further studies have found that Foxa1 and Foxa2 can mediate and enhance the regulation of ERα or androgen receptor (AR) on target genes during the formation of liver cancer, thereby inhibiting (ERα) or promoting (AR) the development of liver cancer." (PMID 35096574, 2021). "Tumor suppressive roles of FoxA1 were also reported in liver cancer and pancreatic cancer." (PMID 32151057, 2020). "FOXA1 is a known contributor to sexual dimorphism in liver cancer in mice." (PMID 28673244, 2017). "Elevated expression of FOXA1 has been observed in liver cancer cells." (PMID 25965836, 2015). "FOXA1 has been reported to promote the expression of Yes-associated protein (YAP), which is a terminal effecter of Hippo/YAP signaling and contributes to cell proliferation of liver cancer." (PMID 25965836, 2015). "FOXA1 is a well-known regulator of EMT, and its involvement in cancer progression has been established in several malignancies, including breast and liver cancers." (PMID 40216647, 2025). "This difference is mainly because of the difference in sex hormones between men and women, and FOXA1 and FOXA2 are also essential for sexual dimorphism in liver cancer." (PMID 38605023, 2024). "In liver cancer, MCM3AP-AS1 is upregulated and can regulate the miR-194-5p/FOXA1 axis to promote tumor growth." (PMID 35929906, 2023). "To further elucidate that HDAC3 controls the expression of Foxa1/2, we knocked down HDAC3 in HUH7 liver cancer cells." (PMID 37752418, 2023). "Interestingly, BNC1 is also a putative ER receptor 1 (ESR1) target as ESR1 was bound in the proximal promoter of BNC1 in T-47D cell line (ENCODE data on UCSC genome browser), raising the possibility that BNC1 might also play a role in sexual dimorphism in liver cancer similar to FOXA1." (PMID 28673244, 2017). "Notably, shRNA-mediated knockdown of FOXA1 and FOXA2, along with sustained ETS1 expression, completely shifted HCC to intrahepatic cholangiocarcinoma development in primary liver cancer mouse models." (PMID 40149719, 2025).
liver cancer (continued). "RNA-seq analyses showed that DEN-induced Srsf3 KO liver cancer in both female and male mice exhibited a significantly reduced expression of Foxa1/2/3 and ERα than DEN-induced Srsf3 WT liver cancer, which could be verified by quantitative RT-PCR." (PMID 40568073, 2025). "Additionally, HBx upregulates MSL2 by activating YAP/FoxA1 signaling, and HBx-elevated MSL2 modulates HBV cccDNA in liver cancer cells, leading to hepatocarcinogenesis." (PMID 35784274, 2022). "Seven TFs (FOXA1, FOXA2, RARG, STAT4, MEF2C, SOX18, and GXS2) have been identified to be likely to affect the metabolism, development, differentiation and proliferation of liver cancer in previous studies." (PMID 29033978, 2017). "As a concrete example, FOXA1 (HNF4A) is a transcription factor important for the specification of the intestine and stomach as well as liver and silencing of HNF4A leads to liver cancer." (PMID 27562343, 2016). "Thus, FGA, FGB, FGG and FGL1 could be important direct target genes of FOXA1 that are involved in EMT of lung and liver cancer specifically." (PMID 24093963, 2013).
lung adenocarcinoma (32 papers, 2013 to 2025). A carcinoma that arises from the lung and is characterized by the presence of malignant glandular epithelial cells. "Squamous transdifferentiation has been linked to drug resistance in human lung adenocarcinomas, and it will be interesting to determine whether FoxA1/2 downregulation plays a role in this process." (PMID 30475207, 2018). "For Instance, the E2 enzyme UBE2T inhibited CD8+ T-cell infiltration and expression of immune-promoting factors (IFN-γ, TNF-α and IL-2) in lung adenocarcinoma by activating the glycolytic pathway upon binding to FOXA1." (PMID 40183093, 2025). "FOXA1 contributed to acquisition of chemoresistance in human lung adenocarcinoma via transactivation of SOX5." (PMID 35498155, 2022). "SOX9 promotes tumorigenesis in lung adenocarcinoma through transcriptionally regulating forkhead box A1 (FOXA1)." (PMID 34899911, 2021). "For example, lncRNA LINC00460 sponged miR-302c-5p and targeted FOXA1 to accelerate progression of lung adenocarcinoma." (PMID 32669970, 2020). "To address this question directly, we used conditional alleles of Foxa1 and Foxa2 to abrogate their function in an autochthonous mouse model of NKX2-1-negative lung adenocarcinoma." (PMID 30475207, 2018). "FoxA1 and FoxA2 are required for initiation and proliferation of NKX2-1-deficient lung adenocarcinoma." (PMID 30475207, 2018). "Although FoxA1/2 can regulate lung adenocarcinoma biology individually in some contexts, their functional redundancy in IMA is consistent with their frequently redundant role in endodermal tissue specification." (PMID 30475207, 2018). "Here, we show that FoxA1 and FoxA2 are required for lung adenocarcinomas to adopt a mucinous, gastric differentiation state in the absence of NKX2-1." (PMID 30475207, 2018). "A systematic computational analysis based on multiple ChIP-Seq and gene expression datasets suggests that FOXA1 is a potentially important negative regulator in the EMT of lung adenocarcinoma." (PMID 24093963, 2013). "Preliminary studies demonstrated that FOXA1 silencing could effectively hinder the invasion and proliferation of certain tumor cells, for example, lung adenocarcinoma A549 cells and lung squamous cell carcinoma cells." (PMID 36393971, 2022). "Forkhead box protein A1 (FOXA1) is a pioneer factor amplified in lung adenocarcinoma (LUAD)." (PMID 35974000, 2022). "Whether FOXA1 overexpression promotes immune evasion in lung adenocarcinoma needs to be further explored." (PMID 35974000, 2022). "Furthermore, NKX2-1 enhances together with FOXA1 survival in lung adenocarcinoma by transcriptional activation of LMO3." (PMID 23637834, 2013). "Thus, we investigated whether PGC1α and FOXA1 participate the induction of ROS-detoxifying enzymes and the maintenance of redox homeostasis in A549 lung adenocarcinoma cells." (PMID 35897813, 2022). "To test the hypothesis that FoxA1/2 are required for lung adenocarcinoma cells to undergo a pulmonary to gastric lineage switch upon loss of NKX2-1 expression, we incorporated conditional alleles of Foxa1 and Foxa2 into a mouse model of NKX2-1-deficient lung adenocarcinoma." (PMID 30475207, 2018). "We propose that aberrant up-regulation of the pioneer factor FOXA1 recommissions both SRR124 and SRR134 in tumor cells, driving SOX2 overexpression in breast and lung adenocarcinoma." (PMID 37738673, 2023). "Other important proteins in this group were the transcription factors FOXA1 and FOXA2 that have been reported as the initiating factors of a cellular transdifferentiation program that generates gastric-like tissue in lung adenocarcinomas." (PMID 39296813, 2021). "Here, we show that the transcription factors FoxA1 and FoxA2 are required for initiation of mucinous NKX2-1-negative lung adenocarcinomas in the mouse and for activation of their gastric differentiation program." (PMID 30475207, 2018). "We show that FoxA1 and FoxA2 regulate the growth and gastric identity of NKX2-1-negative lung adenocarcinoma." (PMID 30475207, 2018).
lung adenocarcinoma (continued). "Moreover, the inhibitory effect of S1PR1 on tumor growth was attenuated by FOXA1 overexpression, suggesting that the role of FOXA1 in mediating the effects of S1PR1 on lung adenocarcinoma cell proliferation." (PMID 39551792, 2024). "Furthermore, we also uncovered the overexpression of some classical oncogenes (FOXA1, PCNA, EZH2) that were reported to mediate carcinogenesis in lung adenocarcinoma along with SUV39H2." (PMID 30348215, 2018). "Taken together, these data show that lack of FoxA1/2 activity at tumor initiation severely impairs the proliferation and long-term growth potential of NKX2-1-negative lung adenocarcinoma." (PMID 30475207, 2018). "Our analysis indicates that FOXA1 is involved in EMT, but may not significantly contribute to lung adenocarcinoma tumorigenesis through direct regulation of target genes." (PMID 24093963, 2013).
pancreatic cancer (27 papers, 2013 to 2025). "For instance, during liver metastasis of pancreatic cancer, the original pancreatic developmental program is replaced by a liver developmental program, achieved through FOXA1-driven enhancer reprogramming." (PMID 40032852, 2025). "For instance, the activation of FOXA1-dependent enhancer drives an embryonic foregut endoderm transcriptional program, rendering pancreatic cancer cells more invasive and facilitating their liver metastasis." (PMID 40032852, 2025). "We also evaluated the genomic distribution of H3K4me1/H3K27ac, FOXA1, and other TF involved in pancreatic tumor development on the CFPAC1 PDAC cell line (GSE54560)." (PMID 39114357, 2024). "In pancreatic cancer, overexpression of FOXA1 promotes the invasion ability by affecting the progression of EMT." (PMID 34991620, 2022). "A recent study focused on pancreatic cancer in the crossing signaling routes, which included prometastatic, pioneer transcription factor FOXA1." (PMID 36012038, 2022). "Previous studies demonstrated that FOXA1/2 proteins suppress EMT by activating E-cadherin expression in pancreatic cancer cells." (PMID 35703180, 2022). "The downregulation of SOX9 did not lead to detectable changes in the expression of the transcription factor FOXA1 in all the six investigated pancreatic cancer cell lines." (PMID 35884771, 2022). "Upon pancreatic cancer development, FOXA1 expression is known to decrease, which drives the epithelial to mesenchymal transition." (PMID 34367349, 2021). "Upregulation of the FOXA1 gene in pancreatic cancer and basal cell carcinoma, due to the transcriptional regulation by the Sonic Hedgehog (SHH) pathway, has also been documented." (PMID 24944681, 2014). "In pancreas cancer FOXA1/2 factors are suppressed by EMT-inducing signals, such as TGFb and DNA methylation." (PMID 24093963, 2013). "For instance, the circumstances under which FOXA1 is activated, leading to liver metastasis of pancreatic cancer, are also unknown." (PMID 40032852, 2025). "Collectively, these results demonstrate that SMARCD3-BAF, in concert with FOXA1, is an important regulator of fatty acid metabolism, and draws a link between SWI/SNF and stem cell-enriched metabolic programs in pancreatic cancer." (PMID 36653361, 2023). "Meanwhile, FOXA1 induced the transcription of lncRNA MIR99AHG and LINC01207 and played a tumor facilitator in pancreatic cancer and head and neck squamous cell carcinoma." (PMID 37277890, 2023). "Using ZBED2 ChIP-seq data from pancreatic cancer cell lines (the only ZBED2 ChIP-seq reported so far), we found a high confidence ZBED2 peak in the FOXA1 promoter (left)." (PMID 36944729, 2023). "Consistent with our findings, several reports have shown that FOXA1 attenuates EMT in breast and pancreatic cancers." (PMID 35897813, 2022). "Numerous reports have revealed that FOXA1 suppresses EMT and cancer metastasis in lung, breast, prostate, gastric, and pancreatic cancers." (PMID 35897813, 2022). "Further, FOXA1 was co-bound at 75% of common SMARCD3-dependent BAF binding sites; these results support a collaboration between the SMARCD3-containing BAF complex and FOXA1 in pancreatic cancer cells." (PMID 36653361, 2023). "Two of the transcripts, FOXA1 (known for its upregulation and pro-metastatic action in pancreatic cancer) and the putative tumor suppressor FOXO6, showed metarrestin exposure-dependent expression changes in KPC tumors and in cultured mouse and human pancreatic cancer cell lines." (PMID 30306263, 2018).